NMNAT1 (nicotinamide nucleotide adenylyltransferase 1)
Diseases named in the same sentence as NMNAT1 in open-access papers (continued):
Sharing a sentence is not in itself a finding about the gene and the disease.
tumor (16 papers, 2016 to 2025). "Interestingly, dePARylated CTCF is associated in a stable protein complex with PARP-1 and NMNAT-1 in cancer cells harboring silenced tumor suppressor genes." (PMID 29029387, 2017). "This modification maintains the nuclear NAD salvage pathway and supports tumor cell survival under glucose deprivation, suggesting that NMNAT1 and its associated metabolic circuitry may also represent attractive targets within the lactylation network of pancreatic cancer." (PMID 41458606, 2025). "Although little is known about NMNAT1 expression in tumors, analyses of cancer genomic databases using the cBioPortal platform showed that a deep deletion of NMNAT1 has been observed in several tumor types." (PMID 38396769, 2024). "Knockdown of NMNAT1 enhanced rRNA transcription, which might facilitate increased ribosome biogenesis and tumour development." (PMID 35421138, 2022). "Eleven human tumor cell lines were tested for NMNAT-1 mRNA expression." (PMID 32392755, 2020). "Other genes were modulated in a different way in all three SCCs (NMNAT1, NMNAT2, NADSYN1, SIRT3, and CD38) or in two tumor types (NNMT, NMNAT3, ENPP2, PNP, and SIRT1)." (PMID 38254798, 2024). "Compared with ubiquitously expressed NMNAT1 and NMNAT3, NMNAT2 mRNA was reported to be mainly expressed in high energy consumption tissues such as brain, heart, skeletal muscle, and some tumor tissues." (PMID 27218101, 2016). "However, NMRGs with significant AUC values (ENPP1, ENPP2, NAMPT, SIRT1, PARP1, NMNAT1, and PNP) were differentially expressed among tumor grades." (PMID 38254798, 2024).
cancer (14 papers, 2016 to 2025). A tumor composed of atypical neoplastic, often pleomorphic cells that invade other tissues. "A high-throughput cytotoxicity screening was performed to identify novel pathways or compounds linked to the cancer-promoting role of NMNAT1." (PMID 34445574, 2021). "We performed a high-throughput cytotoxicity screening to identify novel pathways or compounds linked to the cancer-promoting role of NMNAT1." (PMID 34445574, 2021). "Indeed, high NMNAT1 expression is associated with shorter survival in cancer patients, supporting this hypothesis." (PMID 34445574, 2021). "The activities of DBNQ in NMNAT1-expressing cells (including cancer cells) as well as on the two other isozymes are yet to be established." (PMID 38396769, 2024). "We note that our study complements work by the Luis Parada laboratory describing similar effects of YPEL5 and WDR26 deletion in mouse cells on NMNAT1 amounts, and on modulating the efficacy of a candidate prodrug in the killing of specific types of cancer cells (personal communication)." (PMID 38759627, 2024). "Dysregulations of both NMNAT1 and NMNAT2 have been implicated in cancer." (PMID 34919052, 2021). "All cancer cell lines that were tested expressed NMNAT1 mRNA." (PMID 32392755, 2020). "Our results suggest that NMNAT1 may be worth investigating further as a potential target in cancer therapy." (PMID 32392755, 2020). "We next made use of the anti-cancer agent tiazofurin to probe the functional link between YPEL5 and NMNAT1 stability." (PMID 38759627, 2024). "Future work is required to identify the specific roles of NMNAT1 and NMNAT2 in different cancer types." (PMID 34919052, 2021). "We investigated the metabolic and mechanistic processes that regulate PARP-1-mediated CTCF PARylation in human cancer cell lines and discovered a key role for the expression and activity of β-NAD+ salvage enzymes, NAMPT and NMNAT-1." (PMID 29029387, 2017). "The role of NMNAT1 in cancer cells is not known and its role in cancer cell chemosensitivity has not yet been investigated." (PMID 32392755, 2020). "Due to the lack of specific NMNAT1 inhibitors, however, the role of NMNAT1 in cancer has not yet been investigated." (PMID 32392755, 2020). "However, we and others have observed that NMNAT-1 becomes down-regulated in many cancer cell lines and tumors (data not shown)." (PMID 29029387, 2017).
metabolic disorders (3 papers, 2012 to 2023). "More importantly, FK866 and quercetin consistently corrected NAD+ metabolic disorders, including expressions of NMNAT1, NAPRT, and NAMPT as well as NAD+ and NAD+/NADH levels both in vitro and in vivo." (PMID 35408818, 2022).
infection (2 papers, 2023). The state of being infected such as from the introduction of a foreign agent such as serum, vaccine, antigenic substance or organism. "Knockdown of NMNAT1 in BEAS-2B prior to infection and NR treatment suppressed the cells’ ability to utilize NR for NAD+ synthesis." (PMID 37783679, 2023). "Knockdown of NMNAT1 prior to infection and NR treatment reduced NAD production and partially rescued bacterial replication." (PMID 37783679, 2023). "Deletion of pneumolysin from Spn D39 rescued NMNAT1 expression in BEAS-2B after infection, while NAMPT expression remained unaffected." (PMID 37783679, 2023). "In addition, mRNA of nicotinamide mononucleotide adenylyl transferase 1 (NMNAT1) was significantly downregulated in BEAS-2B cells exclusively during later-stage infection (16 h)." (PMID 37783679, 2023). "To assess how this affects the infection process, we experimentally decreased NAD+ biosynthesis by knockdown of NAMPT or NMNAT1 prior to bacterial infections." (PMID 37783679, 2023). "To assess the role of NAD+ biosynthesis during the infection process, we performed siRNA knockdowns of NAMPT and NMNAT1 48 h prior to infection with Spn D39 (MOI 1, 16 h)." (PMID 37783679, 2023). "To confirm that epithelial NMNAT1 can produce sufficient NAD+ to exert antibacterial activity, we supplemented host cells with NR during infection resulting in a significant increase of intracellular NAD." (PMID 37783679, 2023). "Deletion of the capsule locus (Δcps) and the H2O2 producing pyruvate peroxidase (ΔspxB) did not influence NMNAT1 or NAMPT expression during infection." (PMID 37783679, 2023). "However, while in accordance with the literature inhibition of JAK signaling by Ruxolitinib40 reduced NAMPT expression after Spn D39 infection, expression of NMNAT1 was not affected." (PMID 37783679, 2023). "While we confirmed JAK-dependency of NAMPT upregulation in response to Spn D39 infection using the JAK inhibitor Ruxolitinib, repression of NMNAT1 was not JAK-dependent." (PMID 37783679, 2023). "To determine whether interference with the host NAD+ metabolism is a general process affecting bacterial infections, we performed BEAS-2B infections with Streptococcus agalacticae (S.aga) and non-typeable Haemophilus influenzae (NTHi) and determined the resulting expression of NAMPT and NMNAT1." (PMID 37783679, 2023).
neurodegenerative disease (2 papers, 2020 to 2025). A disorder of the central nervous system characterized by gradual and progressive loss of neural tissue and neurologic function. "Metabolic enzymes NMNAT1 and HAGH (also known as glyoxalase II) clustered together, both involved in cellular processes of importance in neurodegenerative diseases and ageing, including oxidative stress protection." (PMID 40316737, 2025).
peripheral neuropathies (2 papers, 2012 to 2016). "NMNAT1 has been shown to prevent axon degeneration and peripheral neuropathy induced by both paclitaxel and vincristine, suggesting a Wallerian-like mechanism of axon degeneration." (PMID 26808812, 2016).
NMNAT1 also shares sentences with these, for which no sentence is quoted: Retinal dystrophy (4 papers); tauopathy (3); bladder cancer (2); retinitis pigmentosa (2); achromatopsia (1); bacterial infections (1); cardiac hypertrophy (1); choroideremia (1); cone-rod dystrophy (1); esophageal adenocarcinoma (1); frontotemporal dementia with parkinsonism (1); glioblastoma (1); Hyperammonemia (1); hyperopia (1); ischemic stroke (1); liver diseases (1); liver fibrosis (1); musculoskeletal diseases (1); nanophthalmia (1); nervous system disorder (1); neuroblastoma (1); Nystagmus (1); Obesity (1); optic neuropathies (1); ovarian carcinoma (1); pancreatic ductal adenocarcinoma (1); sarcoma (1); sensorineural hearing loss (1); spondyloepiphyseal dysplasia (1); Stillbirth (1).
A further 3 diseases each share a sentence with NMNAT1 in 1 paper.